TRAP1 (TNF receptor associated protein 1)
Diseases named in the same sentence as TRAP1 in open-access papers (continued):
Sharing a sentence is not in itself a finding about the gene and the disease.
tumor (continued). "Interestingly, and in line with this evidence, we have reported that in a large dataset of HGSOC patients, the expression of TRAP1 is inversely correlated to tumor stage and grade, but directly correlated to the overall survival." (PMID 31947673, 2020). "In our case, the observed sequence-dependent synergy might be accounted for in connection with the finding that HSP90 and TRAP1, that are critical regulators of survival of tumour cells, are among the proteins down-regulated by the peptides." (PMID 32585842, 2020). "Given that gamitrinib is prominently known to interfere with the electron transport chain, we hypothesized that gamitrinib and its target TRAP1 could thwart HDAC inhibitor induced activation of tumor respiration." (PMID 32664214, 2020). "Furthermore, TRAP1 is involved in many cellular pathways by disrupting the cell cycle, increasing cell motility, and promoting tumor cell invasion and metastasis." (PMID 33575209, 2020). "The loss of function of TRAP1 increases differentiation and impairs self-renewal, tumorigenesis, and survival of GSCs through the deregulation of mitochondrial respiration, which is essential for GSC stemness, sphere formation, and tumor growth." (PMID 31752169, 2019). "In wild-type IDH1/2 tumors, under hypoxia or pseudohypoxia, like in a TRAP1 upregulated tumor environment, the production of the oncometabolite L-2-HG is frequent via the “promiscuous” reduction of α-KG, catalyzed by lactate dehydrogenase (LDHA) jointly with malate dehydrogenase (MDH)." (PMID 31163702, 2019). "On the other hand, TRAP1 knockdown in tumor cells induces Cyt c releasing from mitochondria into the cytosol and promotes apoptosis, whereas TRAP1 overexpression markedly attenuates the damage induced by oxidative stress and preserves the function of tumor cells." (PMID 31143823, 2019). "Moreover, TRAP1 knockdown in GSCs negatively affects their ability to co-opt for glycolysis (Warburg effect), resulting in decreased tumor growth, cell proliferation and migration, and neurosphere formation, and it also sensitizes GSCs to TMZ." (PMID 31752169, 2019). "Finally, they demonstrate that TRAP1 regulates mitochondrial respiration by binding and inhibiting the functions of the oncogene cSRC, and acting as tumor suppressor." (PMID 31163702, 2019). "Moreover, TRAP1 expression has been found to correlate inversely to tumor grade or stage and correlate directly to the overall survival." (PMID 31540420, 2019). "In order to establish whether TRAP1 expression in human CRCs depends on gene CN variation, TRAP1 CN was analyzed in a cohort of 58 human CRCs at different Tumor, Nodes, Metastasis (TNM) stages." (PMID 31878280, 2019). "Furthermore, the analysis of the National Cancer Institute’s Clinical Proteomic Tumor Analysis Consortium/The Cancer Genome Atlas (CPTAC/TCGA) CRC database showed that TRAP1 polysomy significantly correlates with lymph node involvement." (PMID 31878280, 2019). "TRAP1 is a key regulator of mitochondrial bioenergetics in tumor cells." (PMID 30680959, 2019). "These dual targeting could allow to significantly reduce toxicity: the drug is delivered to the tumor site, which reduce systemic toxicity, and then the targeting of mitochondria could allow a specific inhibition of TRAP1." (PMID 35582577, 2019). "These contrasting observations on the role of Nrf2 and TRAP1 in neoplastic progression suggest that changes in cell redox equilibrium might have different effects on tumorigenesis, probably depending on tumor type and stage." (PMID 30197878, 2018). "Accordingly, tumor cells xenografted with TRAP1-expressing Saos-2 cells had detectable levels of HIF1α, whereas HIF1α downmodulation prevented focus-forming in TRAP1-expressing tumor cells and in mouse embryonic fibroblasts (MEFs) transfected with a TRAP1-expressing construct." (PMID 29621137, 2018).
tumor (continued). "In agreement with this hypothesis, the authors reported an inverse correlation between TRAP1 expression and tumor stage and cervical, bladder and clear cell renal cell carcinomas." (PMID 29621137, 2018). "A similar analysis also revealed that increased Trap1 expression is associated with higher tumor grade, but failed to indicate a significant correlation with overall or relapse-free survival." (PMID 28407697, 2017). "In tumor cell mitochondria, TRAP1 could be part of a chaperone network involving HSP90, heat shock protein 60 (HSP60), and cyclophilin D (CyP-D), one of the best characterized proteinaceous PTP inducers." (PMID 28405578, 2017). "However, higher Trap1 expression correlated with higher tumor grade, which mirrors the functional relationship between Trap1 and tumor onset seen in our mouse model." (PMID 28407697, 2017). "Hence, in this tumor type a strong correlation exists among early TRAP1 induction, Warburg-like metabolic rewiring and protection from oxidative insults, and these adaptations are required for neoplastic progression to malignancy." (PMID 28405578, 2017). "It is reasonable that TRAP1 contributes to tumor progression based on these results." (PMID 28088229, 2017). "In this study, tumor differentiation showed a marginal positive correlation with TRAP1 expression." (PMID 28088229, 2017). "Further investigations will be necessary to dissect the contributions of Trap1 and its impact on cellular metabolism to the different stages of tumor growth, from the earliest stages of tumor initiation to the growth dynamics of tumor masses." (PMID 28407697, 2017). "TRAP1 might also contribute to tumor cell survival under conditions of stress normally encountered during neoplastic growth, such as exposure to redox disequilibria or nutrient shortage." (PMID 28405578, 2017). "Once again, as for primary tumor growth, context seems to be crucial for Trap1." (PMID 28407697, 2017). "In more recent years, the observation that TRAP1 expression is induced in several tumor types, together with its similarity with HSP90, have sparked interest in better understanding the mode of action and the potential role(s) in the neoplastic process played by this mitochondrial chaperone." (PMID 28405578, 2017). "If this is also the case in our tumor model, then clearly it is insufficient to suppress all of the phenotype associated with the absence of Trap1." (PMID 28407697, 2017). "Tumor mitochondria also possess an organelle-specific member of the HSP90 family called TRAP-1." (PMID 28484090, 2017). "Furthermore, TRAP1 and also the mitochondrial pools of Hsp90 and Hsp60 were reported to interact with CyPD and prevent its ability to induce the pore opening in tumor cell models." (PMID 27289382, 2016). "Reciprocally, ClpP co-immunoprecipitated with survivin and TRAP-1 in tumor mitochondria." (PMID 27389535, 2016). "TRAP1 was reported to protect tumor cells from oxidative stress, even if the molecular mechanism remains unclear." (PMID 25564869, 2014). "TRAP-1 has been recently demonstrated as a component of a mitochondrial pathway selectively up-regulated in tumor cells which antagonizes the proapoptotic activity of cyclophilin D and is implicated for the maintenance of mitochondria integrity, thus favoring cell survival." (PMID 24970198, 2013). "g. that TRAP1 is a (surrogate) marker for stressed, thus apoptosis prone, tumor cells." (PMID 22978347, 2012). "The TRAP1/HIF1α axis tunes the bioenergetic activity of mitochondria to the availability of oxygen, mastering cell adaptations to the oxygen paucity that can occur during embryogenesis, ischemia or tumor accrual [1,] and that can propel dyshomeostatic redox conditions." (PMID 40424720, 2025). "Importantly, as a pro-neoplastic role of TRAP1 has been reported in several models, it is conceivable that these observations shed light on general mechanisms through which TRAP1 tetramers contributes to tumor growth." (PMID 40424720, 2025).
tumor (continued). "In addition to pseudohypoxia, TRAP1 protects tumor cells from oxidative stress." (PMID 36902385, 2023). "In addition, in these cases, TRAP1 levels are reduced during tumor progression." (PMID 37508418, 2023). "However, TRAP-1 interacting proteins are not clearly understood but presumed that TRAP-1 acts as a tumor promoter by a few unknown or yet-to-be-identified cellular mechanisms." (PMID 37165028, 2023). "Previous studies demonstrated that TRAP1 may be an anti-tumor molecular target and a key regulator of the reprogramming of energy metabolism in tumor cells, indicating that the change of mitochondrial bioenergy mediated by TRAP1 plays a more common role in tumorigenesis." (PMID 36139663, 2022). "While TRAP1 was not required for tumor initiation, growth, or metastases induced by polyoma middle T-antigen, its loss was associated with a delay of tumor initiation in vivo and in inhibition of proliferation, migration, and invasion in vitro when compared to WT." (PMID 35883436, 2022). "Interestingly, TRAP1 inhibition of mPTP opening was observed not only in tumor cells and hypoxic cellular models but also in NRK-52E kidney cells under high glucose conditions prompting oxidative stress, in H9C2 myocardial cells exposed to extracellular acidification and in C17.2 neural stem cells." (PMID 34829705, 2021). "In tumor cells, TRAP1 may function as an oncogene or tumor suppressor in different types of cancer." (PMID 32215175, 2020). "Moreover, TRAP1 may interact with other master regulator transcription factors that globally regulate tumor cell metabolism, e.g., c-Myc." (PMID 31181660, 2019). "Therefore, the effects of TRAP1 on the neoplastic process could be complex, possibly depending on the tumor type and stage." (PMID 28405578, 2017). "This may be the key mechanism of TRAP1-related tumor progression." (PMID 28088229, 2017). "Taken together, these observations indicate that PTMs of TRAP1 can be a way by which deregulated transduction pathways funnel signals to the mitochondrial bioenergetic machinery, finely tuning its activity during tumor progression in accordance with the metabolic needs of cells." (PMID 28405578, 2017). "Therefore, the anti-oxidant effect of TRAP1 could hamper neoplastic progression in specific tumor types or stages." (PMID 28405578, 2017). "Indeed, TRAP1 knocking-down abolishes tumor growth both in in vitro assays and in xenografts." (PMID 27070090, 2016). "Importantly Hsp90, also the mitochondrial Hsp90 family protein TRAP1 (Hsp75), are abundant in both the intermembrane space and matrix of the mitochondria of tumour cells, but often either undetectable or expressed at very low levels in the mitochondria of most normal tissues." (PMID 27721330, 2011). "Conversely, TRAP1 overexpression and SDH inhibition can protect tumor cells from oxidative stress by preventing the opening of the mitochondrial permeability transition pore (mPTP), inhibiting cytochrome c (Cyt c) release, and suppressing apoptosis." (PMID 41226319, 2025). "The expression of TRAP1 and CAMSAP3 in tumor tissues of dead patients was lower than survival patients." (PMID 38880903, 2024). "All six amplifications that led to a substantial increase in expression in tumor samples were also reported as up-regulated HSP when comparing normal and tumor tissues (CCT3, HSPA6, DNAJA3, TRAP1, DNAJC5, and DNAJC5B)." (PMID 38816397, 2024). "TRAP1 and P4HA1 are highly expressed at the intracellular level, whereas PPARGC1A, EFHD1, and HIGD1A are only expressed by a minority of tumor cells." (PMID 37903487, 2024). "HIGD1A, EFHD1, and PPARGC1A were found to be overexpressed in normal tissue, whereas TRAP1 and P4HA1 were found to be overexpressed in CRC tumor tissue (p < .001)." (PMID 37903487, 2024). "HDCA can restore the TRAP1-dependent downregulation of SDH, reduce tumor cell proliferation, increase mitochondrial superoxide levels, and inhibit tumor growth by selective inhibition of TRAP1." (PMID 36902385, 2023).
tumor (continued). "For example, it was shown that TRAP1, a mitochondrial HSP90 chaperone, supports the expression of multiple mitochondrial enzymes and mitochondrial metabolism in tumor cells." (PMID 37508418, 2023). "In tumor samples both NAD+/NADH ratio and NAD+ are increased following NIC administration and when TRAP1 is ablated, and are dramatically raised when NIC is provided to animals harboring TRAP1 knock-out cells." (PMID 35393510, 2022). "For example, the AP events of several tumor-related genes, such as TRIM7, MLK4, ADNP, and TRAP1, had higher inclusion levels in G1." (PMID 35989380, 2022). "The inhibition of SDH activity is enhanced by TRAP1 ERK1/2-dependent phosphorylation and has antioxidant and antiapoptotic effects in tumor cells, stabilizing the hypoxia-inducible factor 1α (HIF1α), a transcription factor required for tumor cell growth." (PMID 34829705, 2021). "We explored the significance of TRAP1 as a mediator of tumor metabolic programming in the stromal compartment of OSCC and a marker of tumor progression." (PMID 34906113, 2021). "However, TRAP1 may also function as a tumor suppressor in certain tumor cells." (PMID 33575209, 2020). "According to these studies, TRAP1 functions in the regulation of ROS levels and cell metabolism, together with its multiple localizations, suggest that this protein might play a key role in metabolic rewiring of tumor cells, acting as a molecular hub for metabolism-related signaling pathways." (PMID 31947673, 2020). "The authors identified TRAP1 as a crucial regulator of the metabolic switch of tumor cells between OXPHOS and aerobic glycolysis, which correlated with the interaction of TRAP1 and mitochondrial c-Src." (PMID 33575209, 2020). "In tumor mitochondria, Shepherdin interacts with TRAP1 and HSP90, inducing Cyclophilin D-mediated apoptosis in a broad range of tumor cells and multiple xenograft models." (PMID 31947673, 2020). "In fact, TRAP1 can induce or inhibit OXPHOS, and the influence of this regulation on tumour growth is open to discussion." (PMID 31052256, 2019). "However, since cholesterol might be taken up from the interstitium as part of a compensatory mechanism, we hypothesized that the effects of TRAP1 inhibition on tumor cell death might be further enhanced in the presence of compounds that facilitate cholesterol efflux." (PMID 31181660, 2019). "Hence, TRAP1 could regulate the death of normal cells in addition to tumor cells." (PMID 31143823, 2019). "Further hints were provided by recent observations that link TRAP1 phosphorylations to Ras/ERK signaling, a kinase transduction pathway whose hyperactivation has a pivotal importance in a variety of tumor types." (PMID 28405578, 2017). "Relevant clinicopathologic factors including sex, age, tumor size, tumor differentiation, pathologic T, N, and M stage, pathologic TNM stage, lymphovascular invasion, and TRAP1 expression were analyzed in the Cox univariate model." (PMID 28088229, 2017). "Importantly, novel TRAP-1 antagonists are shown to cause sudden collapse of mitochondrial functions and selective tumor cell death, suggesting that this pathway may represent a novel molecular target to improve anticancer therapy." (PMID 24970198, 2013). "Taken together, our data suggest that the analyzed mutations influence TRAP1 chaperone function, affecting its ability to interact with and regulate SDH while reshaping the bioenergetic profile of tumor cells in a manner independent of its ATPase activity." (PMID 40074754, 2025). "Moreover, TRAP1 stabilizes HIF1α via SDH inhibition, promoting the downstream genes that enhance angiogenesis and nutrient supply in proliferating tumor cells." (PMID 41226319, 2025). "Also, a correlation analysis between TRAP1 and mt-signature transcript levels was performed using the TCGA COAD tumour dataset of GEPIA2." (PMID 39210159, 2024).
tumor (continued). "Functionally, TRAP1 was shown to directly promote the activity of the electron transport chain to facilitate cellular respiration in low-nutrient conditions and to promote MYC-dependent tumor cell migration." (PMID 37508418, 2023). "As a result, TRAP1 deletion was shown to have no or minimal effect on normal development of mice, but can effectively inhibit growth of tumor cells." (PMID 38098505, 2023). "Extending the study on understanding the role of TRAP-1 in regulating its interactors may provide additional clues on how TRAP-1 favors metabolism and tumor progression." (PMID 37165028, 2023). "TRAP1 inhibits mitochondrial complex II, downregulates SDH activity, and promotes tumor growth." (PMID 36902385, 2023). "Consequently, it is difficult to reconcile an oncogenic function of TRAP1 with its activation by SIRT3, if the latter plays a tumor suppressor role." (PMID 35393510, 2022). "SIRT3 overexpression does not further decrease tumor growth in a TRAP1-null background, whereas NIC treatment almost abrogates it." (PMID 35393510, 2022). "Moreover, overexpression of TRAP1 in CAFs decreased SRC compared to that of vector cells, which increased the viability of tumor cells." (PMID 34906113, 2021). "TRAP1 inhibits the activation of AMPK and its substrate ULK1, maintains cytoskeletal dynamics, releases the cell motility effector FAK by limiting autophagy during bioenergetic stress, further overcomes metabolic stress and promotes tumor cell metastasis." (PMID 33575209, 2020). "The results showed that the expression of HSP90AA1, HSP90AB1, and TRAP1 was positively correlated to the tumor purity, while that of HSP90B1 was not." (PMID 33145341, 2020). "Overall, these data indicate that in combination it may be that various salivary MV biomarkers including HSP90α, HSP90β, TRAP1, HSP105, VEGF-C, annexin V and laminin-332 could be of use in tumour detection, staging and prognosis." (PMID 32054041, 2020). "Activation of liver X receptor (LXR) by a clinically validated LXR agonist, LXR623, along with the TRAP1 inhibitor, gamitrinib (GTPP), results in synergistic reduction of tumor growth and cell death induction in a broad range of solid tumors, which is rescued by exogenous cholesterol." (PMID 31181660, 2019). "A moderate TRAP1 staining by immunohistochemical analysis was found in normal bronchial mucosa, as opposed to the adjacent tumor." (PMID 29621137, 2018). "In this scenario, the possibility of connecting TRAP1 chaperone activity with oncogenic transduction pathways, such as hyperactive Ras/ERK signaling, opens new avenues to elucidate in which tumor types and stages the metabolic rewiring prompted by TRAP1 is pivotal for neoplastic progression." (PMID 28405578, 2017). "Indeed, this dynamic interaction between TRAP1 and SDH could provide a very flexible response to fit the redox equilibrium and the pseudohypoxic status required for neoplastic progression, acting as a general oncogenic mechanism, whereas SDH mutations remain confined to very specific tumor subsets." (PMID 25564869, 2014). "We and others have identified in different tumor cell models a number of putative TRAP1 protein clients, including metabolic enzymes, transporters, OXPHOS components and other chaperones, pointing to the possibility of a multiplicity of TRAP1 interactions under different biological conditions." (PMID 40424720, 2025). "Hence, nanocarriers to deliver TRAP-1 inhibitors were developed in which iron oxide nanoparticles (IONs) were conjugated to the Hsp90 inhibitor geldanamycin (GA) and the mitochondria localization signal (MLS) peptide to enable selective tumor targeting." (PMID 37007005, 2023). "Therefore, the reduction of TRAP1 protein levels by CVM-1125 may act to obstruct the downstream signaling axis, which contributes to the inhibition of tumor growth and the induction of apoptosis via caspase-3." (PMID 37351538, 2023).